NTRK1 (neurotrophic receptor tyrosine kinase 1)
Diseases named in the same sentence as NTRK1 in open-access papers (continued):
Sharing a sentence is not in itself a finding about the gene and the disease.
lung cancer (continued). "Together, these data demonstrate that Ntrk1 expression can modulate KP lung cancer biology as well as the immune microenvironment via Jak1 signaling to promote the expression of immunosuppressive molecules including PD-L1." (PMID 30986992, 2019). "Taken together, our data indicate that Ntrk1 and Ntrk3 both regulate downstream signaling to AKT and MAPK in KP lung cancer cells, but the regulation of cell growth by Ntrk1 mainly occurs via MAPK signaling cascades." (PMID 30986992, 2019). "In some solid tumor types such as lung cancer, Ntrk1 genetic rearrangements occur infrequently (~1–3% of lung adenocarcinomas), leading to fusion proteins with constitutive kinase activity." (PMID 30986992, 2019). "ALK, ROS1, RET, and NTRK1 fusions are observed frequently in lung cancer." (PMID 40223139, 2025). "Based on these findings, we hypothesize that missense mutations in NTRK1 and ZRSR2 may contribute to primary resistance to Osimertinib in non‐small cell lung cancer (NSCLC) with EGFR mutations through modulation of the PI3K pathway." (PMID 39907312, 2025). "The management of lung cancer (LC) requires the analysis of a diverse spectrum of molecular targets, including kinase activating mutations in EGFR, ERBB2 (HER2), BRAF and MET oncogenes, KRAS G12C substitutions, and ALK, ROS1, RET and NTRK1-3 gene fusions." (PMID 38966170, 2024). "NTRK1 gene rearrangement can promote tumor progress and drug resistance in lung cancer." (PMID 34912722, 2021). "Furthermore, NTRK1–3 fusions occur infrequently in lung carcinomas." (PMID 33963267, 2021). "However, the occurrence of the NTRK1–3 fusions in lung carcinomas is extremely rare." (PMID 33963267, 2021). "Thus, we determined that Ntrk1 is a novel regulator of immune functionality in KP lung cancer, and combinatory treatment strategies could circumvent PD-1 blockade resistance." (PMID 30986992, 2019). "Thus, the regulation of PD-L1 and other immunosuppressive molecules downstream of Jak/Stat signaling cascades may be a unique function of Ntrk1 in KP mutant lung cancer." (PMID 30986992, 2019). "These evidences are in agreement with our findings and suggest NTRK1 as a potential target of cisplatin resistance in NSCLC, although further studies are needed on this gene in lung cancer." (PMID 38351531, 2024). "Genetic testing for advanced nonsmall cell lung cancer (NSCLC) includes EGFR, ALK, ROS1, BRAF, MET, HER-2, RET, NTRK1/2/3, PI3K, and PD-L1." (PMID 35368895, 2022). "Previously, in lung cancer or other tumors, it has been found that MPRIP can interact with neurotrophic tyrosine receptor kinase 1 (NTRK1), platelet-derived growth factor receptorβ (PDGFRB), and proto-oncogene such as RAF1." (PMID 36290895, 2022). "In our lung cancer cohort, we also observed a 0.2% of FGFR family (mostly FGFR3) fusions and 0.02% of NTRK1/3 gene fusions." (PMID 36369474, 2022). "In lung cancer, for example, seven different gene fusions involving the NTRK1 gene have been described that lead to the constitutive activation of the TrkA tyrosine kinase domain." (PMID 33620682, 2021). "Fusions involving the neurotrophin receptor tyrosine kinase genes (NTRK1, NTRK2, and NTRK3) recur in cancers like gliomas, secretory breast cancer, and lung cancer." (PMID 35127532, 2021). "In this study, we have established in vivo imaging models for brain tumors that mimic brain metastases for EGFR‐mutant lung cancer, HGF‐dependent gastric cancer, and NTRK1‐fusion‐positive colon cancer." (PMID 29125233, 2017). "In summary, we have established an in vivo imaging system for brain tumor models of EGFR‐mutant lung cancers, HGF‐dependent gastric cancers, and NTRK1‐fusion‐positive colon cancers." (PMID 29125233, 2017).
lung cancer (continued). "We have established an in vivo imaging model for brain tumors for the epidermal growth factor receptor (EGFR)‐mutant lung cancer, the HGF‐dependent gastric cancer, and for colorectal cancer harboring the NTRK1 gene fusion." (PMID 29125233, 2017). "In particular, NTRK1 has been found to fuse with tropomyosin in colon cancer, TPM3, TPR, and TFG in thyroid cancer, and MPRIP and CD74 in lung cancer." (PMID 24647444, 2014). "Thus, we conducted a correlation study between FGF11 and EGFR (19DEL, L858R), EGFR (Exon 20ins), KRAS (G12C), ALK, ROS1, BRAF, NTRK1/2/3, MET, and RET, which are all recommended by the NCCN guidelines for the diagnosis of nonsmall cell lung cancer." (PMID 37250453, 2023). "We utilized pentaplex panel testing for 23 lung carcinomas, 23 sarcomas, 4 thyroid carcinomas, 3 salivary gland tumors, and 3 pancreatic carcinomas with oncogenic gene translocations (ALK: 31; ROS1 10; RET: 9; NTRK1: 2; NTRK3: 4)." (PMID 37686416, 2023). "Finally, we identified two lung cancer patients with MET+ and NTRK1+ tumors, respectively, who responded well to crizotinib treatment." (PMID 36369474, 2022). "Results of our study analyzing pan-TRK expression in lung carcinoma demonstrate very low positivity across different histologic types, without any confirmed NTRK1–3 fusions using an RNA-based sequencing method." (PMID 33963267, 2021). "The requirement for co-development and co-approval of CDx in order to get TKIs approved against these RTK (ROS1, RET, NTRK1, AXL, PDGFR-α) rearrangement lung cancer represents the daunting challenge to successfully translate decades of basic science research into benefit of cancer patients." (PMID 24744988, 2014). "However, it will not be pragmatically feasible to perform phase Ib/II clinical trials of discrete combination regimens for each individual therapy-resistant, rare molecular subset of lung cancer (e.g., ROS1-, RET-, and NTRK1-3-rearranged NSCLC) and for each distinct genomic mechanism of resistance." (PMID 37923925, 2023). "The Ion AmpliSeq RNA Lung Cancer Research Fusion Panel is based on an amplicon target enrichment approach that allows amplification and detection of 70 known fusion transcripts for the ALK, RET, ROS1, and NTRK1 genes using a couple of primers specific of each fusion." (PMID 28970558, 2017). "Although there are several cell lines harboring NTRK fusion, including CUTO-3 lung cancer cells with MPRIP-NTRK1 fusion and MO-91 acute myeloid leukemia (AML) cells with ETV6-NTRK3 fusion, KM12 is the only available colon cancer cell line harboring NTRK1 fusion." (PMID 26716414, 2016). "However, the regulatory roles of NTRK1 and DDR2 amplification on lung cancer cell behaviors have not yet been characterized." (PMID 36499051, 2022).
glioma (53 papers, 2013 to 2025). A benign or malignant brain and spinal cord tumor that arises from glial cells (astrocytes, oligodendrocytes, ependymal cells). "Although a prior study observed NTRK1 fusions at an incidence of 1% in glioblastoma, we didn’t find any NTRK1 fusion in our series of 59 tumor samples from patients operated for low and high-grade gliomas." (PMID 39087020, 2024). "NTRK2 fusions were found in ten cerebral diffuse low-grade and high-grade gliomas (DLGGs and DHGGs, respectively), and NTRK1 fusions were found in one cerebral desmoplastic infantile ganglioglioma and one spinal DHGG." (PMID 39014476, 2024). "Most pediatric cases had NTRK2-fusions (69%, 9 cases), while NTRK1-fusions were found in most adult glioma cases (68%, 15 cases)." (PMID 35295612, 2022). "Given the little understanding in the function of NTRK2/3 fusions in glioma, we emphatically describe NTRK1 fusions here." (PMID 34671307, 2021). "Several NTRK1/2/3 fusions have been reported in GBM and preclinical studies have proven that NTRK fusions are potential driver mutations in some high-grade gliomas." (PMID 33330081, 2020). "Most adult NTRK-fused gliomas involved NTRK1 (68.2%, 15/22), with NTRK3 (18.2%, 4/22) and NTRK2 (13.6%, 3/22) comprising subsets of cases." (PMID 32665022, 2020). "Here we present deep profiling of whole proteome, phosphoproteome and transcriptome in two high-grade glioma (HGG) mouse models driven by mutated RTK oncogenes, PDGFRA and NTRK1, analyzing 13,860 proteins and 30,431 phosphosites by mass spectrometry." (PMID 31420543, 2019). "We further show that in vivo delivery of RCAS-gRNA plasmids for the Bcan-Ntrk1 gene fusion led to high-grade glioma tumor formation." (PMID 29654229, 2018). "We have observed that, in human glioma patients and in our mouse model, the NTRK1 gene fusions led to overexpression of the chimeric NTRK1 transcripts." (PMID 29654229, 2018). "We show that the chromosomal deletion generating the Bcan-Ntrk1 gene fusion can drive the formation of high-grade gliomas and confers sensitivity to entrectinib, an experimental TrkA inhibitor." (PMID 28695888, 2017). "Both cell lines expressed the Bcan-Ntrk1 fusion transcript and readily formed high-grade gliomas with short latency when orthotopically implanted into nude mice." (PMID 28695888, 2017). "The clonal lines harbouring the intra-chromosomal deletion and expressing Bcan-Ntrk1, clones #8 and #5, generated high-grade gliomas with full penetrance, closely resembling tumours derived from the mixed parental line." (PMID 28695888, 2017). "To explore the therapeutic potential of entrectinib in Bcan-Ntrk1-driven gliomas in an in vivo setting, we then orthotopically injected BNN4 tumour cells into nude mice and randomly divided the animals into entrectinib or vehicle treatment groups." (PMID 28695888, 2017). "Experimental validation of such targeting strategies would require models (such as glioma stem cells or xenografts) derived from patient tumors with the NTRK1-fusion." (PMID 24647444, 2014).
glioma (continued). "Although NTRK1/2/3 fusions are rare (≈1% of gliomas), they may act as oncogenic drivers, particularly in higher-grade tumors." (PMID 41301694, 2025). "We have also observed that the NTRK gene involved in the rearrangement differs in frequency by age, with pediatric gliomas having a high percentage of rearrangements involving NTRK2 (69.2%), and adult gliomas having a high percentage of rearrangements involving NTRK1 (68.2%)." (PMID 32665022, 2020). "We then evaluated whether the RCAS-Bcan-Ntrk1 gRNA-pair was able to induce glioma formation when directly delivered in vivo into Gtv-a; hGFAP-Cre; LSL-Cas9; p53lox/lox pups." (PMID 29654229, 2018). "To determine whether Bcan-Ntrk1 positive brain tumours are addicted to TrkA kinase signalling, we derived cell lines from two independent gliomas arising in mice implanted with gRNA-BN1/Cas9-nucleofected aNSCs (hereafter referred to as BNN4 and BNN2)." (PMID 28695888, 2017). "We show that one such rearrangement, an microdeletion resulting in a fusion between Brevican (BCAN) and Neurotrophic Receptor Tyrosine Kinase 1 (NTRK1), is a potent oncogenic driver of high-grade gliomas and confers sensitivity to the experimental TRK inhibitor entrectinib." (PMID 28695888, 2017). "The beneficial effect of NTRK2 overexpression on OS confirms recent data reporting that loss of mRNA expression of both NTRK1 and NTRK2 correlates with poor prognosis in patients with high-grade glioma, but our analysis adds a location-specific link to the picture." (PMID 27782828, 2016). "Studies have simulated four relatively rare chromosomal rearrangements with unknown oncogenic potential in human brain glioma and have found that one of the chromosomal deletions results in fusion between BCAN and NTRK1, which promotes the formation of highly invasive glioma." (PMID 32337264, 2020). "Molecular profiling revealed that 72% of gliomas harbored NTRK2 fusions, while NTRK1 and NTRK3 fusions were identified in 13% and 15% of cases, respectively." (PMID 40647390, 2025). "A variety of NTRK fusion types (NTRK1, NTRK2, and NTRK3) have also been described in pediatric high-grade gliomas." (PMID 39087020, 2024). "NTRK1-3, ROS1, and ALK fusion genes in infantile glioma are targetable, therefore, nationwide adaptation of NGS to evaluate these fusion genes and more extensive accumulation of clinical data are required." (PMID 33673070, 2021). "Some of these gliomas feature alterations in genes such as ROS1, ALK, MET, and NTRK1–3." (PMID 41155159, 2025). "Moreover, NTRK1 gene fusions are oncogenic and prevalent in some tumors, such as NSCLC, melanoma, glioma, and thyroid cancers." (PMID 38351531, 2024). "While induction of the Bcan-Ntrk1 rearrangement readily resulted in high-grade gliomas, we never observed tumours after implantation of Fgfr3-Tacc3, Sec61g-Egfr or Gga2-Prkcb positive cell populations within the timeframe of analysis (150 days)." (PMID 28695888, 2017). "Additionally, the classification now recognizes infant-type hemispheric glioma as a separate high-grade glioma category characterized by a unique molecular profile, including fusion genes involving ALK, ROS1, NTRK1/2/3, or MET, predominantly seen in newborns and infants." (PMID 38137148, 2023). "Last but certainly not least, fusion oncoproteins involving the TRKA, TRKB, and TRKC tyrosine kinases (which are encoded by NTRK1, NTRK2, and NTRK3, respectively) have been identified across nine tumor types, including sarcoma, melanoma, gliomas, thyroid, lung, colon, breast, head and neck cancers)." (PMID 29455648, 2018).
melanoma (48 papers, 2007 to 2025). A malignant, usually aggressive tumor composed of atypical, neoplastic melanocytes. "In this driverless setting, we revealed rare oncogenic drivers known from melanoma or other cancer types and identified rare actionable tyrosine kinase mutations in NTRK1, RET and VEGFR1." (PMID 36980598, 2023). "In this driverless setting, we revealed rare oncogenic drivers known from melanoma or other cancer types and identified rare actionable tyrosine kinase mutations in NTRK1/3, RET and VEGFR1." (PMID 36980598, 2023). "Retrospective studies of spitzoid neoplasms have found activating fusions involving BRAF, RET, ROS1, ALK, or NTRK1 in 39% of melanomas with spitzoid morphology and just over 50% of Spitz nevi and atypical Spitz tumors." (PMID 32123303, 2020). "Among 751 cases, they identified three cutaneous primary melanomas (3/395; 0.8%) and one mucosal/paramucosal melanoma (1/113; 0.9%) harbouring NTRK1 or NTRK2 gene fusions." (PMID 31738427, 2019). "NTRK1 is located at 1q23.1, and an increased copy number involving that site is considered a potential oncogenic alteration in patients with malignant melanoma and hepatocellular carcinoma, but gene amplification including 1q23.1 is not a common structural variant in esophageal or gastric cancers." (PMID 41516212, 2025). "NTRK1 fusions were detected even in eight Spitz nevi and in four spitzoid melanomas." (PMID 34830218, 2021). "Rearrangements in several genes, including BRAF, RET, ROS1, ALK, NTRK1, and NTRK3, have been characterized in subsets of melanoma." (PMID 32123303, 2020). "Increasingly, gene fusions involving various kinases, including ALK, ROS1, BRAF, RAF1, NTRK1, and NTRK3 have been identified within melanomas, and these fusion-positive melanomas often display spitzoid morphology." (PMID 32483240, 2020). "Unlike most common and congenital nevi and malignant melanomas, they lack oncogenic BRAF and NRAS mutations and harbor tumorigenic HRAS mutations or kinase gene fusions involving ALK, BRAF, MET, NTRK1, NTRK3, RET, and ROS1 in a mutually exclusive pattern." (PMID 34830218, 2021). "Genetic fusions involving anaplastic lymphoma kinase (ALK), neurotrophic receptor tyrosine kinase 1 (NTRK1), ROS proto-oncogene 1 (ROS1), rearranged during transfection (RET), and B-Raf proto-oncogene serine/threonine kinase (BRAF) genes are frequently observed in this type of melanoma." (PMID 39202970, 2024). "In contrast to Spitz tumors with fusions of ALK, NTRK1, and ROS1, which are usually compound with a prominent epidermal component, epidermal involvement in the RAF1-fused melanomas was typically limited or absent." (PMID 32123303, 2020). "In addition, more recently, NTRK1, NTRK2, and NTRK3 kinase fusions have been detected in a very small proportion (<1%) of metastasizing non-spitzoid melanomas of adults, suggesting the opportunity of Trk inhibition therapy for this group of patients." (PMID 32466202, 2020).